XIAP (X-linked inhibitor of apoptosis)
Diseases named in the same sentence as XIAP in open-access papers (continued):
Sharing a sentence is not in itself a finding about the gene and the disease.
primary immunodeficiency (23 papers, 2013 to 2025). "Primary immunodeficiency gene panel testing revealed a nonsense variant XIAP c833C > G p.(Ser278*), which generates a premature stop codon at exon 2 (of total 7 exons)." (PMID 40301935, 2025). "X-linked inhibitor of apoptosis protein (XIAP) deficiency is a primary immunodeficiency caused by mutations in the XIAP gene, and is estimated to occur in 1–2 per million live births." (PMID 36329240, 2023). "Neonatal or infantile-onset IBD is often associated with primary immune deficiency disorders, especially those caused by mutations in IL-10, XIAP, NCF2, IPEX, and TTC7A." (PMID 35783276, 2022). "Patients with X-linked inhibitor of apoptosis (XIAP) deficiency present with a primary immunodeficiency characterized by hemophagocytic lymphohistiocytosis, severe infections, splenomegaly, and cytopenia." (PMID 36524121, 2022). "X-linked lymphoproliferative syndrome type 2 (XLP2) is a rare genetic primary immunodeficiency disease (PIDD) caused by loss-of-function mutations in the XIAP (also known as BIRC4) gene that lead to deficiency of the X-linked inhibitor of apoptosis protein." (PMID 37205951, 2021). "X-linked lymphoproliferative syndrome type 2 (XLP2) is a rare genetic primary immunodeficiency disease caused by mutations in the XIAP gene that lead to deficiency of the X-linked inhibitor of apoptosis protein." (PMID 37205951, 2021). "This association of immunosuppressive phenomena with bacterial dysbiosis in cancer has also been supported by the detection of dysbiotic intestinal microbiota in patients with primary immunodeficiency, such as X-linked inhibitor of apoptosis (XIAP) deficiency." (PMID 31450675, 2019). "Our results and those of others suggest that XIAP-deficient individuals are unable to clear infection due to primary immunodeficiency and persistent inflammation, leading to XLP-2 and lethality." (PMID 29386580, 2018). "X-linked lymphoproliferative syndrome type-2 (XLP-2) is a primary immunodeficiency disease attributed to XIAP mutation and is triggered by infection." (PMID 29386580, 2018). "Mutations in the X-linked inhibitor of apoptosis (XIAP) are associated with a rare primary immunodeficiency." (PMID 27703456, 2016). "XIAP deficiency is a rare primary immunodeficiency, also known as X-linked lymphoproliferative syndrome type 2 (XLP-2), caused by mutations in the XIAP (BIRC4) gene." (PMID 32514016, 2020). "X-linked lymphoproliferative syndrome (XLP) is a rare primary immunodeficiency disease that can be divided into two types: SAP deficiency (XLP1) and XIAP deficiency (XLP2), caused by mutations in the SH2D1A and XIAP genes, respectively." (PMID 31754776, 2020). "In five patients we detect a primary immunodeficiency or enteropathy, with clinical consequences (XIAP, CYBA, SH2D1A, PCSK1)." (PMID 32081864, 2020). "At that time, primary immunodeficiency (PID) gene panel testing ordered by his outpatient clinical immunologist was reported and revealed a hemizygous nonsense variant XIAP c833C > G p.(Ser278*), which generates a premature stop codon at exon 2 (of total 7 exons)." (PMID 40301935, 2025). "X-linked lymphoproliferative syndrome type-2 (XLP-2) is a primary immunodeficiency disease linked to the absence of X-linked inhibitor of apoptosis protein (XIAP) due to XIAP gene mutation." (PMID 29386580, 2018). "As a primary immunodeficiency disease, the only curative treatment for XLP-2 patients is allogeneic hematopoietic cell transplantation (HCT) to restore expression of XIAP in hematopoietic stem cells (HSCs), yet outcomes are limited by the toxicity associated with transplantation." (PMID 29386580, 2018).
non-small cell lung carcinoma (22 papers, 2004 to 2025). A group of at least three distinct histological types of lung cancer, including non-small cell squamous cell carcinoma, adenocarcinoma, and large cell carcinoma. "The other combination therapy that synergistically targets XIAP was demonstrated in non-small cell lung cancer preclinical studies using XIAP-targeting short hairpin RNA (shRNA) and celecoxib." (PMID 30250647, 2018). "Taken together, our findings suggest that the combination of TRAIL and LA synergistically induces apoptosis in non-small cell lung cancer cells via the inhibition of XIAP/NF-κB as a potent TRAIL sensitizer." (PMID 29772677, 2018). "miR-215 and miR-192 promoted apoptosis through the XIAP pathway in non-small cell lung cancer." (PMID 26317904, 2015). "Also in non-small cell lung cancer, the high expression level of XIAP is involved in the pathogenesis of this cancer." (PMID 25120954, 2014). "Similarly, a correlation between XIAP mRNA and protein levels was previously reported in non-small-cell lung carcinomas." (PMID 15328523, 2004). "miR-4782-3p impedes cell proliferation in non-small cell lung cancer (NSCLC) by targeting USP14, ZEB2, and XIAP." (PMID 37917013, 2023). "Using two cancer cell lines [triple negative breast cancer (TNBC) and non-small cell lung cancer (NSCLC)] that highly expressed CCT2, depletion of this subunit decreased anti-apoptotic proteins like XIAP and inhibited phosphorylation of AKT and GSK3." (PMID 35602608, 2022). "An antisense oligonucleotide directed against XIAP (AEG35156) is in phase I/II clinical trials for patients with pancreatic, breast, non-small cell lung cancer, AML, lymphoma and solid tumours in which docetaxel is the drug of choice." (PMID 25328816, 2013). "However, it was observed that cells with lower levels of XIAP, i.e., the triple-negative breast cancer cell line MDA-MB-231, were less sensitive to SNIPER-induced Bcl-xL degradation, compared with cells expressing higher levels of XIAP, i.e., non-small cell lung cancer cell line A549." (PMID 35954440, 2022). "Substrate 2 inhibited non-small cell lung cancer (NSCLC) cell growth and induced apoptosis by destabilising proteins including survivin, XIAP, and RIP1 without altering their mRNA levels." (PMID 41155147, 2025). "Also in colorectal carcinomas as well as in non-small cell lung carcinoma (NSCLC) and in hepatocellular carcinoma there was no inverse relationship between XIAP expression and percentage of apoptotic cells." (PMID 24281211, 2010).
osteosarcoma (21 papers, 2006 to 2025). A usually aggressive malignant bone-forming mesenchymal neoplasm, predominantly affecting adolescents and young adults. "For instance, circKIF5B and circ_0000282 promote osteosarcoma progression by specifically modulating the miR-192/XIAP axis." (PMID 40087755, 2025). "Another study on osteosarcoma showed that SM164 combined with adriamycin treatment can downregulate XIAP expression, thereby enhancing the antitumor activity of adriamycin." (PMID 41122967, 2025). "The one report examining BMP regulation of XIAP in cancer cells showed that BMPRII in osteosarcoma cell lines stabilized the expression of XIAP." (PMID 27048361, 2016). "Additionally, another study demonstrated that miR-192 inhibits osteosarcoma cell proliferation and induces apoptosis by interacting with XIAP." (PMID 40087755, 2025). "Similarly, in osteosarcoma cells, cinobufagin has been found to significantly reduce the expression of XIAP." (PMID 38044583, 2024). "Tumor progression-associated proteins (VEGF, MMP-9, Cyclin-D1, C-FLIP, MCL-1, and XIAP) may serve as therapeutic targets for inhibition of osteosarcoma progression." (PMID 31238539, 2019). "Our current results also presented that both PD98059 (MEK/ERK pathway inhibitor) and miltefosine (AKT inhibitor) both inhibit the expression of tumor progression-associated proteins (VEGF, MMP-9, Cyclin-D1, C-FLIP, MCL-1, and XIAP) in osteosarcoma U-2 OS cells in vitro." (PMID 31238539, 2019). "Our gene expression results are strongly supported by previous studies, which showed that cell death stimulation with daunorubicin, cisplatin, or p14ARF over-expression in U2OS osteosarcoma cells resulted in RelA mediated transcriptional repression of pro-survival genes, Bcl-xL or XIAP." (PMID 21347231, 2011). "The preliminary exploration on the molecular mechanism of MEX3A in osteosarcoma cells showed that the induction of apoptosis needs the participation of a series of apoptosis- associated factors, such as upregulation of Caspase 3, Caspase 8 and HSP60, downregulation of HSP27 and XIAP." (PMID 33827584, 2021). "Upregulation of miR-192 suppresses the progress of osteosarcoma through targeting USP1, TCF7, and XIAP." (PMID 33614788, 2021). "XIAP ASO, AEG35156, was reported to suppress XIAP expression and induce apoptosis in several pediatric cancer cell lines including osteosarcoma, neuroblastoma, rhabdomyosarcoma, and Ewing’s sarcoma cells." (PMID 31652776, 2019). "Together these observations suggest that, for TNFα to kill osteosarcoma cells, RIPK1 is required and the activities of cIAP1 and XIAP must be diminished." (PMID 27129149, 2016). "Chemotherapeutic agents, including methotrexate, cisplatin and doxorubicin, are widely employed in osteosarcoma treatment, but their anticancer efficacy may be hindered by anti‐apoptotic proteins such as BCL‐2, MCL‐1, c‐FLIP and XIAP." (PMID 40889216, 2025). "Furthermore, we were able to show that viscum, TT, and viscumTT led to downregulation of BIRC5 and XIAP in AML, Ewing-sarcoma, and osteosarcoma." (PMID 28791312, 2017). "The IAP antagonists SM-164, GDC-0152 and LCL161, which efficiently target XIAP and cIAPs, sensitized cells from most osteosarcomas to killing by low levels of TNFα but not TRAIL." (PMID 27129149, 2016). "We infer that, in osteosarcoma cells, IAP antagonist-mediated degradation of cIAP1 enables formation of the ripoptosome and activation of caspase-8, which can stimulate caspase-3/7 activity if the IAP antagonist permits this by relieving XIAP-mediated inhibition." (PMID 27129149, 2016).
myeloma (16 papers, 2009 to 2022). "In this regard, the administration of LCL161 has significantly reduced X-linked inhibitor of apoptosis protein (XIAP) activity and cellular inhibitor of apoptosis protein-1 (cIAP1) levels in both sensitive and resistant myeloma cells." (PMID 33669515, 2021). "As overexpression of miR-340-5p had induced a significant increase of apoptosis in myeloma cells, luciferase reporter assay was employed to verify if XIAP, an inhibitor of apoptosis, is a direct target of miR-340-5p." (PMID 31064412, 2019). "In multiple myeloma (MM) cells, HHT showed anti-myeloma effect with concomitant targeting of the myeloma-promoting molecules, Mcl-1, XIAP, and beta-catenin." (PMID 29788973, 2018). "XIAP is highly expressed in myeloma cells and is induced by IL-6 and IGF-1-mediated activation of NF-κB/MAPK/PI3K pathways." (PMID 26009993, 2015). "Indeed, high XIAP expression has been demonstrated in primary myeloma plasma cells and cell lines and yielded larger tumors than myeloma cells with XIAP knock-down in a mouse xenograft model." (PMID 31064412, 2019). "Therefore, the tumor suppressor activity of miR-340-5p was mediated by targeting, and hence downregulation, of XIAP in myeloma." (PMID 31064412, 2019). "Indeed, clinical experience with SNS-032 in patients with chronic lymphocytic leukemia and multiple myeloma identified neutropenia as the dose-limiting side-effect, thought to be a consequence of decreased expression of Mcl-1 and XIAP." (PMID 28938529, 2017). "Inhibition of MDM2 by RNAi or by the MDM2/XIAP dual inhibitor MX69 significantly increased the sensitivity of resistant HMCLs and primary MM samples to bortezomib and other anti-myeloma drugs, demonstrating that MDM2 can modulate drug response." (PMID 35326742, 2022). "Inhibition of MDM2 by RNAi, or by the MDM2/XIAP dual inhibitor MX69, significantly enhanced the sensitivity of resistant HMCLs and primary MM samples to bortezomib and other anti-myeloma drugs, demonstrating that MDM2 can modulate drug response." (PMID 35326742, 2022). "Conversely, methylation-mediated silencing of miR-340-5p enhanced myeloma plasma cell proliferation via upregulation of CCND1 and MAPK signaling (NRAS/MEKK1/MEKKK3/p-ERK) in addition to enhancing myeloma cell survival by targeting XIAP." (PMID 31064412, 2019).
neuroblastoma (15 papers, 2008 to 2023). Neuroblastoma (NB) is the most common solid, extracranial childhood tumor. "In the current study, we showed that aggressive, high-risk MYCN-amplified neuroblastoma cells tend to express a higher level of XIAP." (PMID 37874199, 2023). "From a screen of IAP inhibitors, first-in-class ARTS mimetic A4 was most effective against high-risk and high XIAP-expressing neuroblastoma cells, and least toxic toward normal liver- and bone marrow–derived cells, compared with pan-IAP antagonists." (PMID 37874199, 2023). "Having shown that A4 was the most potent compound in suppressing high-risk neuroblastoma in vitro, we sought to investigate the effect of targeting XIAP by A4 in vivo using PDX models of neuroblastoma." (PMID 37874199, 2023). "A4 demonstrates promising efficacy in prolonging the survival of high-risk, MYCN-amplified neuroblastoma PDXs despite having weaker binding affinity for XIAP than Smac mimetic BV6." (PMID 37874199, 2023). "This suggests that binding and degradation of XIAP is necessary for inducing apoptosis in high-risk neuroblastoma cells." (PMID 37874199, 2023). "Taken together, our results strongly suggest XIAP as a viable target for the suppression of high-risk, resistant neuroblastoma." (PMID 37874199, 2023). "XAF1 is a potent antagonist of anti-apoptotic XIAP and Survivin whereby Survivin is associated with high-risk neuroblastoma." (PMID 27097110, 2016). "This suggests that specific targeting of XIAP could be a potential treatment strategy for high-risk neuroblastoma." (PMID 37874199, 2023). "The decrease of LC3-II levels caused by XIAP knockdown was also observed in human neuroblastoma SK-N-SH cells and in MCF10A cells, where we also confirmed that we could rescue the negative effects of XIAP knockdown by overexpressing XIAP in knockdown cells." (PMID 25669656, 2015). "Taken together, XIAP-specific antagonist A4 not only prolongs and improves the overall survival of high-risk neuroblastoma PDXs as a single agent, but also shows translational potential to augment the efficacy of cytotoxic agents in killing high-risk neuroblastoma cells when used in combination." (PMID 37874199, 2023). "We found that the ARTS mimetic A4, an XIAP-specific antagonist, demonstrated the best efficacy across a panel of commercial and patient-derived neuroblastoma cell lines." (PMID 37874199, 2023). "In summary, binding and degradation of XIAP by ARTS mimetics is a novel and effective therapeutic strategy against high-risk neuroblastoma either alone or in combination with current standard-of-care agents." (PMID 37874199, 2023). "To explore the implication of the anti-apoptotic effects of XIAP in this observed improvement, we analysed the effects of overexpression of XIAP in cultures of the human neuroblastoma cell line SH-SY5Y (SH-SY5YXIAP+)." (PMID 36769152, 2023). "This suggested that XIAP is highly expressed in most neuroblastoma tumors and is positively correlated to MYCN amplification status." (PMID 37874199, 2023). "In this study, we evaluated the effectiveness and therapeutic value of different IAP antagonists on neuroblastoma and present a new XIAP-specific targeting strategy using ARTS mimetics." (PMID 37874199, 2023). "This difference in mechanism for suppressing XIAP resulted in different responses in neuroblastoma cells." (PMID 37874199, 2023). "Among the six IAP antagonists, XIAP-specific antagonists A4 and B3 showed highest potency against neuroblastoma cells across the panel of cell lines with the lowest IC50 achieved (2–15 μmol/L)." (PMID 37874199, 2023). "Neuroblastoma cells containing endogenous luciferase-tagged XIAP were generated using CRISPR/Cas9 gene editing to knock-in a bioluminescent tag at endogenous loci of XIAP." (PMID 37874199, 2023). "It was especially effective against high XIAP-expressing cell lines which also happened to be MYCN-amplified, a classical hallmark of aggressive and resistant neuroblastoma." (PMID 37874199, 2023).